ACE (angiotensin I converting enzyme)
Diseases named in the same sentence as ACE in open-access papers (continued):
Sharing a sentence is not in itself a finding about the gene and the disease.
lung carcinoma (53 papers, 1981 to 2026). "Recent studies have reported that high cumulative doses of ACE inhibitors (ACEIs) can significantly increase lung cancer incidence, with a higher risk observed among Asian patients." (PMID 41490177, 2026). "During our MR analysis of six lung cancer cohorts, genetic proxies for ACE inhibition were positively associated with a higher risk of lung cancer." (PMID 37799968, 2023). "Genetic proxies for ACE inhibition are positively associated with a higher risk of lung cancer among the European population." (PMID 37799968, 2023). "Association between genetically proxied ACE inhibition and risk of overall and subtype-specific breast, colorectal, prostate, and lung cancer risk." (PMID 35113855, 2022). "There is considerable evidence of a relationship between polymorphisms in ACE and gastric cancer, lung cancer, prostate cancer, and cancer in general." (PMID 34285715, 2021). "To more accurately assess the potential relationship between the ACE I/D polymorphism and the risk of lung cancer, we performed a meta-analysis using all eligible published studies." (PMID 33579229, 2021). "In recent years, there have been many studies on the role of ACE I/D polymorphism in the risk of lung cancer, but there were some contradictions among the results of these studies." (PMID 33579229, 2021). "Compared with the other studies, this study is more comprehensive regarding the relationship between ACE I/D polymorphism and lung cancer risk." (PMID 33579229, 2021). "To further assess the association between ACE I/D polymorphism and lung cancer risk, we performed a meta-analysis of 12 case–control studies, including 2181 cases and 2126 controls." (PMID 33579229, 2021). "Some studies showed an obvious trend of the ACE ‘II’ genotype with increased risk of lung cancer, whereas other studies have shown that the DD genotype of ACE contributes to a higher risk of lung cancer." (PMID 33579229, 2021). "We evaluated the association between the I/D polymorphism in the ACE gene and lung cancer risk by performing a meta-analysis." (PMID 33579229, 2021). "Conversely, a study on a large population-based cohort that used ACE inhibitors suggested an increased risk for developing lung cancer, particularly among patients undergoing treatment for more than five years." (PMID 32503281, 2020). "However, ACE inhibition has known side effects, e.g., dry cough and angioedema, and has been linked to higher rates of lung cancer." (PMID 40988601, 2025). "Since then, research has focused on the potential carcinogenic effect of antihypertensive drugs, especially with the ongoing evidence suggesting that thiazide diuretics predispose to the development of skin cancer or that ACE-Is are associated with lung cancer." (PMID 38542413, 2024). "In addition, ACE-Is lead to accumulation of substance P in lung cancer tissue, which is associated with proliferation and angiogenesis." (PMID 38542413, 2024). "Finally, the use of ACE inhibitors has been linked with the statistically significant increase in lung cancer incidences, especially in a subgroup of patients with over ten years of drug use." (PMID 32429547, 2020). "Tachykinins belong to a family of neuropeptides, including substance P, neurokinin A, neurokinin B, neurokinin K, and neurokinin Y. A previous study indicated that substance P could potentially act as a mediator in the association between ACE inhibition and lung cancer (Muñoz and Coveñas, 2014)." (PMID 37799968, 2023). "Furthermore, the insertion/deletion (I/D) polymorphism of ACE gene has been linked to the pathogenesis and progression of human cancers and the lowest serum ACE levels were correlated with poorer prognosis and higher relapse rates in lung cancer." (PMID 33353148, 2020). "Lung cancer growth and metastasis can decrease pulmonary vessels, reducing ACE activity in lungs and serum, explaining the reduced ACE expression in lung cancer tissues." (PMID 41490177, 2026).
lung carcinoma (continued). "The Se-peptides demonstrated strong antioxidant activity (ABTS: 66.30%, FRAP: 54.93%), ACE inhibition (83.87%), and cytotoxicity against A549 lung cancer cells (85.88% viability)." (PMID 40941104, 2025). "Research indicates that ACE is also one of the key nodes connecting pulmonary fibrosis and lung cancer." (PMID 40248693, 2025). "Multiple studies suggest that various anti - tumor drugs, including dasatinib, act as potential inhibitors for treating NCP - related comorbidity of pulmonary fibrosis and lung cancer through nodes like ACE." (PMID 40248693, 2025). "A clinical trial carried out by Bar and other researchers revealed that lung cancer patients with high baseline ACE levels had much better outcomes than those with low ACE levels." (PMID 39040892, 2024). "Our MR analysis found a correlation between ACE inhibition (or ACEI-induced cough) and a higher risk of lung cancer among the European population." (PMID 37799968, 2023). "However, another study has shown that the ACE ‘ID’ genotype might increase the risk of lung cancer." (PMID 33579229, 2021). "ACE immunostaining was dramatically decreased in lung cancer tissues confirmed by a 3-fold decrease in ACE activity." (PMID 31877149, 2019). "The increase in ZPHL/HHL ratio in lung cancer tissues was consistent with greater conformational changes of ACE." (PMID 31877149, 2019). "Primary lung cancer growth and lung cancer metastases decrease lung vascularity reflected by dramatic decreases in both lung and serum ACE activity." (PMID 31877149, 2019). "Limited analysis of the conformational ACE fingerprint in normal lung tissue and lung cancer tissue form the same patient suggested a remote effect of tumor tissue on ACE conformation and/or on “field cancerization” in a morphologically-normal lung tissues." (PMID 31877149, 2019). "Progress in ACE biology over the last decade prompted us to re-evaluate the status of ACE (ACE phenotype) in lung cancer." (PMID 31877149, 2019). "Consistent with the reduced expression of ACE in the lung tumor tissue, serum levels of ACE are decreased in lung cancer patients to a greater extent than in other cancers." (PMID 28791183, 2017). "ACE inhibition is a frontline, FDA-approved, therapy for cardiovascular diseases yet is associated with significant side effects, including higher rates of lung cancer." (PMID 40988601, 2025). "ACE-Is may be involved in lung cancer pathogenesis by determining the accumulation of bradykinin in the lung." (PMID 38542413, 2024). "We also investigated the relationship between ACE inhibition and specific subtypes of lung cancer." (PMID 37799968, 2023). "Although such compensation may attenuate genetic effects, it could not explain the association between specific genetic proxies of ACE inhibition (or ACEI-induced cough) and the risk of lung cancer." (PMID 37799968, 2023). "Although the exact mechanism by which ACE inhibition contributes to the occurrence of lung cancer remains unclear, the genetic proxy for ACE inhibition does not affect the development of lung cancer by reducing SBP." (PMID 37799968, 2023). "In summary, our study showed that ACE I/D polymorphism did not increase or decrease the risk to lung cancer." (PMID 33579229, 2021). "A recent report on lung ACE reported tissue ACE expression decreases in lung cancer." (PMID 34359878, 2021). "When analyzed together, these results from clinical and pre-clinical studies suggest that AT1 receptor blockers, in contrast to ACE inhibitors, might be putative therapeutic tools to impair lung cancer progression." (PMID 32503281, 2020). "Furthermore, ACE inhibitors that block endogenous Ang II production or ARBs that attenuate Ang II activity efficiently reduced EMT in lung cancer." (PMID 31133857, 2019).
lung carcinoma (continued). "This hypothesis potentially explains the observed effects of ACEIs on lung cancer incidence and the reduced ACE expression in lung cancer tissues, while accounting for the lack of association between ACE gene polymorphisms and lung cancer." (PMID 41490177, 2026). "Given the potential toxicity of targeting nAChR or Src46,47, the inhibition of the RA system by ACE inhibitors or AGTR1 antagonists that are prescribed to hypertensive patients without major complications would be an effective strategy for the prevention of lung cancer in smokers." (PMID 37258578, 2023). "Although previous studies have revealed that ACE may have a certain effect on the etiology of lung cancer, our results suggest that these effects may not be caused by ACE gene mutations." (PMID 33579229, 2021). "The exact pathogenetic role of ACE in the etiology of lung cancer remains unclear." (PMID 33579229, 2021). "Moreover, considering that this polymorphism may affect serum ACE levels and ACE levels may affect the risk of lung cancer, the risk for lung cancer is not directly caused by ACE gene mutations." (PMID 33579229, 2021). "Conversely, hypoxia regulates RAS-related proteins expression in somatic tissues and cells, up-regulating Ang II, ACE, and AT1 receptor, while down-regulating ACE2 and AT2 receptor in lung carcinoma cells." (PMID 32503281, 2020). "Most components of the RAS including angiotensinogen, angiotensin-converting enzyme, ACE) and angiotensin receptors are expressed locally in a wide variety of tumors, including in lung cancers." (PMID 31133857, 2019). "A BP-enriched fraction obtained from Spirulina was originally studied for its pharmacological activity on the angiotensin I-converting enzyme (ACE) and its anti-proliferative effect in lung cancer cells." (PMID 31244874, 2019). "Our study has important clinical implications, shedding new light on the concept of repositioning ACE inhibitors and ARBs as a novel class of lung cancer chemopreventive agents without the potential deleterious toxicities found in metabolic disorders." (PMID 37258578, 2023). "To rule out the possibility that ACE inhibition indirectly affects the incidence of lung cancer by reducing SBP, we conducted an MR analysis to explore the relationship between SBP and the risk of lung cancer." (PMID 37799968, 2023). "Contrarily, several studies demonstrated that patients treated with angiotensin-converting enzyme (ACE) inhibitors but not angiotensin receptor blocker (ARB) for more than 5 years have a higher lung cancer incidence." (PMID 35911555, 2022). "Given this complex landscape, we hypothesize that ACE’s role in lung cancer may be regulated by RNA expression levels rather than gene mutations, aligning with our mutation landscape analysis." (PMID 41490177, 2026). "Indeed, a negative correlation between lung cancer and circulating ACE activity was shown half a century ago, in a limited number of patients." (PMID 34359878, 2021). "Interestingly, cathepsin D and TPA, but not chymase, renin and ACE (not shown), were expressed in both A549 and H460 lung cancer cells and TPA levels were upregulated in NSCLC cells, as compared with NHBE cells." (PMID 33380422, 2021). "However, this MR analysis was subject to the following three assumptions: SNPs and ACE inhibition have a robust correlation; no confounder affects ACE inhibition and lung cancer; and that SNPs affect the development of lung cancer only through ACE inhibition, indicating no pleiotropic imbalance." (PMID 37799968, 2023).
Sepsis (52 papers, 2008 to 2025). Sepsis is defined as life-threatening organ dysfunction caused by a dysregulated host response to infection. "We investigated renin as a biomarker for sepsis-associated ARDS instead of ACE because renin is upstream to both ACE and ACE216." (PMID 38509149, 2024). "This is contrary to a study in adults with sepsis, which demonstrated that lower ACE concentrations on Day 1 were associated with worse outcomes." (PMID 37308975, 2023). "In this study, we found that midkine was remarkedly elevated in sepsis, and was associated with increased expression of ACE and severity of lung injury both in patients and CLP models." (PMID 33639987, 2021). "We aimed to evaluate the change of midkine in sepsis and its association with angiotensin-converting enzyme (ACE) system, as well as the mechanism by which midkine induced in sepsis and lung injury." (PMID 33639987, 2021). "Low levels of ANG II and ACE activity on day 1 have been previously reported in patients with sepsis and appear associated with a poor prognosis." (PMID 32028998, 2020). "In addition, insertion/deletion angiotensin-converting enzyme (ACE) gene polymorphisms have been linked to an increased risk of sepsis in I allele carriers." (PMID 38716051, 2024). "Indeed, decreased ACE activity has been found in the subgroup of septic shock patients with acute lung injury, consistent with the dominant pulmonary expression of ACE and suggesting a predominant role of sepsis-associated (pulmonary) endotheliopathy." (PMID 38877367, 2024). "Analysis of insertion/deletion ACE gene polymorphisms by reverse hybridization analysis revealed that the DD genotype may have a positive effect on the development of sepsis in healthy children." (PMID 38716051, 2024). "In addition, sepsis-induced endothelial injury has been associated with ACE deficiency, preventing the conversion of AngI to AngII, contributing to a relative decrease in AngII plasma levels, which was observed in patients with septic shock." (PMID 34359936, 2021). "Plasma midkine was significantly elevated in sepsis, and was closely associated with ACE system." (PMID 33639987, 2021). "Moreover, previous studies have demonstrated that endotoxemia causes a decrease in ACE function, and, finally, ACE function has been shown to be important in sepsis outcomes." (PMID 30368243, 2018). "Prolonged ACE inhibition can impair antigen presentation and neutrophil activity, raising concerns about vaccine responsiveness and sepsis outcomes." (PMID 40722848, 2025). "Studies revealed that targeted inhibition of midkine expression in the lung samples suppresses ACE activity through Notch 2 receptors and decreases the secretion of angiotensin II, thereby improving sepsis-induced ALI." (PMID 36593471, 2023). "We note that reduced ACE activity has been described in patients with ARDS and sepsis and was associated with adverse outcome." (PMID 36418458, 2022). "On the one hand, ACE inhibitors can cause prerenal AKI when afferent blood supply is compromised, which is present in sepsis as a result of disruption of renal perfusion." (PMID 33704529, 2021). "This is in line with the results from a study on severe sepsis that indicated low levels of Ang II and ACE on day 1 as predictors of mortality." (PMID 35498160, 2021). "In sepsis, the importance of these findings was emphasized by the demonstration of elevated levels of ACE+-EMPs and ACE+-EMPs/EMPs in the blood of patients who developed ARDS." (PMID 32486469, 2020). "Bronchoalveolar lavage fluid (BALF) ACE was elevated in ARDS patients with infectious causes of lung injury, possibly reflecting endothelial damage or local increase in ACE production in response to sepsis." (PMID 33233715, 2020). "However, while dysregulation of ACE in sepsis has been discussed, there is limited focus on the downstream products of Ang II and the role of the non-classic RAS cascade." (PMID 40880342, 2025).
Sepsis (continued). "Similarly, ACE expression in human lung tissue is reduced in sepsis patients relative to control tissues 32,33." (PMID 40093086, 2025). "Similarly, ACE expression in human lung tissue is reduced in sepsis patients relative to control tissues." (PMID 41439503, 2025). "Additionally, both ACE and ACE2 are involved in the AT1 and AT2 receptor pathways, which are implicated in the development and progression of sepsis-associated ARDS." (PMID 38509149, 2024). "A total of 15% of hospitalized patients with a poor clinical outcome were associated with the rs1800629 polymorphism of TNF-α that is strongly correlated with sepsis, while 6.7% of patients were associated with a less severe form of CAP, due to the rs1799752 I/I genotype of ACE." (PMID 37630611, 2023). "Levels were related to sepsis severity and the angiotensin-converting enzyme (ACE) system." (PMID 36834869, 2023). "Additionally, ACE inhibitors and ARB’s have been shown to be associated with reduced mortality in patients with sepsis." (PMID 35035441, 2022). "Pulmonary midkine inhibition ameliorates sepsis induced lung injury, which might via ACE/Ang II pathway and the participation of Notch 2 in the stimulation of ACE." (PMID 33639987, 2021). "Midkine inhibition ameliorates sepsis induced lung injury, which might via ACE/Ang II pathway and the participation of Notch 2 in the stimulation of ACE." (PMID 33639987, 2021). "Plasma soluble ACE activity is decreased in ARDS patients and the authors speculated that the decreased ACE levels in sepsis-induced ARDS are due to the presence of circulating inhibitors of ACE." (PMID 33233715, 2020). "Therefore, low expression levels of AngII and ACE are valuable in predicting the mortality of patients with severe sepsis." (PMID 24940436, 2014). "Together, these findings suggest that sepsis causes RAS imbalance by inhibiting ACE2 and activating ACE, thereby altering the levels of their catalytic products and the activity of downstream signaling pathways in the heart, which may be involved in the pathogenesis of SIC." (PMID 39320524, 2024). "However, these values continued to decrease over the first 72 h, and thus we postulate that extensive endothelial injury may result in release of ACE reservoirs early in sepsis, with subsequent exhaustion over time." (PMID 37308975, 2023). "However, the explicit role of midkine in sepsis and the mechanism by which midkine regulates ACE remains unclear." (PMID 33639987, 2021). "Therefore, it would be of interest whether discontinuation and exchange of therapy with ACE inhibitors (e.g., by calcium channel blockers) in AML patients who are at risk of suffering from sepsis is recommendable." (PMID 33704529, 2021). "Additionally, another study had data that did not support an association of the ACE gene I/D polymorphism with susceptibility or mortality in severe sepsis or with sepsis-induced ARDS in Spanish patients." (PMID 33233715, 2020). "In mice models, an influence of the RAS components ACE and ACE2 was already described in severe acute lung injury provoked by sepsis or acid aspiration." (PMID 36979408, 2023). "Lower sepsis-related organ failure assessment (SOFA) scores, rs4291, serum ACE and rs4646994 were all considered as risky factors for SS patients." (PMID 28336767, 2017). "However, mice deficient in ACE, which would therefore have less angiotensin, have less lung injury following acid aspiration or sepsis, and at least one clinical study suggests that people who do not express the ACE gene variant associated with increased enzyme activity are at lower risk of ARDS." (PMID 23584753, 2008). "However, ACE also drives pro-inflammatory signaling via Ang II–AT1R activation, inducing cytokine release (TNF-α, IL-6, IFN-γ) and ROS production, potentially exacerbating inflammation in sepsis or viral infections." (PMID 40722848, 2025).